NGF (nerve growth factor)
Diseases named in the same sentence as NGF in open-access papers (continued):
Sharing a sentence is not in itself a finding about the gene and the disease.
disc degeneration (12 papers, 2008 to 2025). "In vitro and in vivo studies found nerve growth factor (NGF) increased during disc degeneration, where it is thought to contribute to both innervation of degenerating discs and neuronal sensitization." (PMID 31747924, 2019). "A multivariate analysis was performed, adjusted for age and sex, with the presence of disc herniation and disc degeneration as independent variables, and the NGF level as the dependent variable." (PMID 25069717, 2014). "In our study, we evaluated the correlation between NGF levels and the presence of disc herniation after adjusting for age, sex and the degree of disc degeneration, and this analysis showed significant correlation." (PMID 25069717, 2014). "Our data support further development of anti-NGF therapeutics to manage pain in degenerative disc disease." (PMID 24650225, 2014). "Then we assessed the correlation between protein levels of NGF and disc degeneration." (PMID 25069717, 2014). "However, correlation between disc degeneration and NGF levels is still open to question and further investigation is needed to reach a conclusion." (PMID 25069717, 2014). "From these results we could at least exclude strong correlation between NGF levels and disc degeneration." (PMID 25069717, 2014). "Aoki and colleagues have suggested that NGF-dependent neurons may be the nerve population responsible for discogenic pain based on findings from studies of disc degeneration in rats." (PMID 18637190, 2008). "Lastly, neurotrophic factors include NGF and brain-derived neurotrophic factor (BDNF), which are upregulated during disc degeneration and promote nerve ingrowth and pain." (PMID 41304859, 2025). "Levels of NGF in the discs were compared between 1) patients with herniated discs (herniated group) and those with other lumbar degenerative disc diseases (non-herniated group), and 2) low-grade and high-grade degenerated discs." (PMID 25069717, 2014). "The correlation between NGF expression and disc degeneration is not clear cut." (PMID 25069717, 2014).
epilepsy (12 papers, 2018 to 2025). A brain disorder characterized by episodes of abnormally increased neuronal discharge resulting in transient episodes of sensory or motor neurological dysfunction, or psychic dysfunction. "Nerve growth factor (NGF) has also been proven to be implicated in the development of epilepsy." (PMID 36145334, 2022). "The anti-epilepsy drug carbamazepine has also been suggested to be neuroprotective by acting through the TrkA receptor to augment NGF signaling in diabetic mice, thus mimicking NGF signaling." (PMID 41002420, 2025). "Studies on animal models of epilepsy have proposed potential involvement of dysregulations of neurotrophins, such as BDNF, NGF and NT-3, in human epilepsy." (PMID 35996194, 2022). "Disturbance of glucose metabolism, nerve growth factor (NGF) and m-TOR signaling have been associated with the pathophysiology of epilepsy." (PMID 36145334, 2022). "Regarding the effect of NGF on astrocytes, it has been shown that in epilepsy model, it can limit their proliferation through p75NTR." (PMID 31996225, 2020).
breast tumor (11 papers, 2010 to 2025). "In particular, protein and immunological expression of NGF have been reported in the majority of human breast tumors, making it a broader diagnostic potential than ER or HER-2." (PMID 36354700, 2022). "Our analysis on breast tumors suggested that NGF (nerve growth factor)-induced tumor cell proliferation might be associated with tumor-related growth factor pathways through ceRNA." (PMID 29565967, 2018). "In breast tumor data, MACPath shows that extensive ceRNA relationship changes in tumor are associated with previously under-characterized tumorigenic crosstalk e.g. between nerve growth factor and other tumor-related growth factor pathways." (PMID 29565967, 2018). "Anti-NGF antibodies or small interfering RNAs against NGF inhibited breast tumor growth and metastasis in xenograft models." (PMID 33392191, 2020). "For example, human breast tumor biopsies display widespread immunoreactivity for nerve growth factor (NGF, a prototypical neurotrophic factor and well-recognized molecular mediator of pain), and in xenografted mice, NGF blockade inhibits both tumor growth and metastasis." (PMID 37274254, 2023). "Importantly, NGF can stimulate mitogenesis and pro-survival signaling in triple negative breast cancer cells (MDA-MB-231) which lack ER, PR and HER2 and are the most difficult type of breast tumor to treat." (PMID 24212627, 2011).
diabetic retinopathy (11 papers, 2011 to 2024). "In retinal neurodegeneration, a thinning of the peripapillary nerve fiber layer of the retina is found in diabetic retinopathy, while the protective effects of nerve growth factor (NGF) on retinal ganglion cells are disrupted." (PMID 39027475, 2024). "To explain the therapeutic effect of CARB in treating diabetic retinopathy, we focused on agents with a pivotal role in neuronal proliferation, maturation and survival, such as the neurotrophic agent NGF." (PMID 31736682, 2019). "Since retinal NGF was reported to promote neuronal survival in diabetic retinopathy and since CARB was documented as a neuroprotective agent in many neurologic disorders, this study explored the possible retinal protective action of CARB in diabetic mice." (PMID 31736682, 2019). "In diabetic retinopathy, the ratio of proNGF/NGF is increased, suggesting a greater pro-inflammatory and pro-apoptotic activity." (PMID 29626212, 2018). "It appears that the imbalance of proNGF/NGF is critical for various early endpoints for diabetic retinopathy including retinal inflammation, neurodegeneration, vascular permeability and development of acellular capillaries." (PMID 26807305, 2015). "In the next sections, we will examine evidence from literature on how imbalance in proNGF/NGF ratio correlates with early characteristics of diabetic retinopathy including: retinal inflammation, neuro- and microvascular degeneration." (PMID 26807305, 2015). "Restoring the balance of NGF/proNGF and targeting proNGF/p75NTR axis may be potential therapeutic strategy to prevent early signs of diabetic retinopathy." (PMID 26807305, 2015). "In the present work, we performed a small pilot study investigating the feasibility of whether changes in proNGF/NGF levels observed in vitreous will be mirrored in serum and thus provide rationale to examine proNGF as a biomarker for diabetic retinopathy." (PMID 25853140, 2015). "Among the factors involved in diabetic retinopathy (DR), nerve growth factor (NGF) and vascular endothelial growth factor A (VEGFA) have been shown to affect both neuronal survival and vascular function, suggesting that their crosstalk might influence DR outcomes." (PMID 36291113, 2022). "In diabetic retinopathy altered expression and activity of MMP-7 has been shown to impair the homeostatic balance between the pro-form and cleaved active form of NGF and contribute to neurovascular dysfunction." (PMID 25158309, 2014).
osteosarcoma (11 papers, 2016 to 2025). A usually aggressive malignant bone-forming mesenchymal neoplasm, predominantly affecting adolescents and young adults. "This study investigated the influence of NGF on the migration and metastasis of osteosarcoma patients (88 cases) as well as the underlying molecular mechanisms, based on RNA-sequencing and gene expression data from a public database (TARGET-OS)." (PMID 38816365, 2024). "Nerve growth factor (NGF) has been implicated in the metastasis and progression of various cancers; however, the mechanism by which NGF promotes metastasis in osteosarcoma has yet to be elucidated." (PMID 38816365, 2024). "Functionally, NGF released by osteosarcoma cells up-regulates ICAM-1/VCAM-1 on circulating monocytes, accelerates extravasation, and skews differentiation toward an M2 phenotype via TrkA–ERK signalling." (PMID 41142827, 2025). "Converging mechanistic and translational observations support a model in which NGF/BDNF signaling shapes osteosarcoma biology at three interdependent levels: tumor cells, the vascular–stromal interface, and immune effectors." (PMID 41383615, 2025). "Transcriptomic interrogation of patient datasets shows NGF and TrkA expression enriched in osteosarcoma relative to other neurotrophins and receptors, with NGF associated with migratory and metastatic programs." (PMID 41567220, 2025). "Focused osteosarcoma studies now place NGF/Trk signaling as a driver of malignant progression with microenvironmental consequences." (PMID 41383615, 2025). "The purpose of this article is to define NGF/BDNF as shapers of the osteosarcoma immune microenvironment and to delineate biomarker−guided therapeutic opportunities for clinical testing." (PMID 41383615, 2025). "The fact that FAK inhibitors reversed NGF-enhanced c-Src phosphorylation suggests that in human osteosarcoma, NGF activates the FAK and c-Src signaling pathways and in so doing promotes VCAM-1-regulated monocyte adhesion." (PMID 39247831, 2024). "Our data suggest that the effects of NGF in facilitating the growth of osteosarcoma involve the expression of M2 macrophage markers." (PMID 39247831, 2024). "Transfecting osteosarcoma cells with an miR-513c-5p mimic significantly reduced NGF-induced monocyte adhesion, VCAM-1, and CD206 expression." (PMID 39247831, 2024). "In summary, the upregulation of NGF in osteosarcoma is positively correlated with the clinical stage of the disease and enhances the metastatic potential." (PMID 38816365, 2024). "Exposure to NGF markedly suppressed miR-513c-5p generation in two osteosarcoma cell lines in a concentration-dependent manner." (PMID 39247831, 2024). "In summary, this study demonstrated that NGF augments VCAM-1-dependent monocyte adhesion within the osteosarcoma microenvironment and facilitates M2 macrophage polarization by inhibiting miR-513c-5p expression via the FAK and c-Src signaling cascades." (PMID 39247831, 2024). "Despite the important role of the NGF/TrkA axis in tumor metastasis, researchers have yet to identify the specific molecular mechanisms by which it acts on osteosarcoma or the effectiveness of larotrectinib in this context." (PMID 38816365, 2024). "The effects of NGF were examined in vivo by generating an osteosarcoma cell line that overexpressed NGF (143B/NGF)." (PMID 39247831, 2024). "Transfection of osteosarcoma cells with a miR-92a-1-5p mimic significantly reduced NGF-induced MMP-2 mRNA and protein expression, as well as the cell migration and invasion abilities." (PMID 38816365, 2024). "Exposing M0 macrophages to NGF-treated osteosarcoma conditioned medium was also shown to enhance polarization to the M2 phenotype, but not to the M1 phenotype." (PMID 39247831, 2024). "The results obtained from commercially available tissue arrays revealed a strong correlation between NGF expression levels and the clinical stage of osteosarcoma." (PMID 38816365, 2024).
osteosarcoma (continued). "NGF also enhanced VCAM-1-dependent monocyte adhesion within the osteosarcoma microenvironment by down-regulating miR-513c-5p levels through the FAK and c-Src cascades." (PMID 39247831, 2024). "NGF induced MMP-2 expression in both osteosarcoma cell lines as well as increases in MMP-2 mRNA and protein levels in a dose-dependent manner." (PMID 38816365, 2024). "In both osteosarcoma cell lines, exposure to NGF at various concentrations (30, 50, or 100 ng/mL) revealed the concentration-dependent suppression of miR-92a-1-5p expression." (PMID 38816365, 2024). "Larotrectinib emerged as a potential drug for the treatment of NGF-mediated metastasis in osteosarcoma." (PMID 38816365, 2024). "In osteosarcoma samples, NGF and TrkA mRNA expression levels were higher than those of BDNF, NT-3, NT-4, TrkB, or TrkC." (PMID 38816365, 2024). "In this study, osteosarcoma cells (143B and 143B/NGF) were orthotopically implanted into the right tibia of mice, after which the body weight and tumor volume was recorded weekly." (PMID 38816365, 2024). "In osteosarcoma patients, the expression of NGF was significantly higher than that of other growth factors." (PMID 38816365, 2024). "We also determined that larotrectinib inhibits NGF-mediated effects in vitro and in vivo, which suggests the potential of using larotrectinib to develop novel therapeutic agents for osteosarcoma." (PMID 39247831, 2024). "Taken together, these findings suggest that the NGF-promoted growth of osteosarcoma involves macrophage infiltration and M2 macrophages expression." (PMID 39247831, 2024). "In the current study, our aim was to elucidate the means by which NGF enhances monocyte adhesion in the osteosarcoma microenvironment." (PMID 39247831, 2024). "Analysis was performed on 88 osteosarcoma tissue samples from the Genomic Data Commons (GDC) data portal with the aim of establishing NGF expression levels and elucidating its role in osteosarcoma." (PMID 38816365, 2024). "In summary, NGF is positively correlated with MMP-2 in human osteosarcoma tissue and NGF promotes osteosarcoma cell metastasis by upregulating MMP-2 expression." (PMID 38816365, 2024). "This analysis revealed that NGF promotes osteosarcoma cell metastasis by upregulating MMP-2 expression." (PMID 38816365, 2024). "The screening of candidate targets in NGF-treated osteosarcomas revealed that the NGF-induced upregulation of VCAM-1 was more pronounced than that of ICAM-1 or CCL2." (PMID 39247831, 2024). "The mechanism of endogenous NGF in osteosarcoma was elucidated by establishing an overexpressing NGF osteosarcoma cell line (143B/NGF) to confirm protein expression using Western blot analysis." (PMID 38816365, 2024). "In cellular experiments, NGF-stimulated osteosarcoma conditional medium was shown to facilitate macrophage polarization from the M0 to the M2 phenotype." (PMID 39247831, 2024). "Our findings provide further evidence that larotrectinib impedes NGF-induced osteosarcoma cell migration in vitro and lung metastasis in vivo." (PMID 38816365, 2024). "Some studies have pointed out that the expression of NGF in osteosarcoma tissues is significantly higher than that of other growth factors, and cellular experiments have demonstrated that NGF promotes the metastasis of osteosarcoma cells by up-regulating matrix metalloproteinase 2 expression." (PMID 40860871, 2025). "Mechanistic map of NGF/BDNF signaling nodes relevant to osteosarcoma immunity." (PMID 41383615, 2025). "Studies suggest that NGF may promote the progression of malignant tumours such as osteosarcoma by activating TrkA or p75 receptors." (PMID 40860871, 2025). "Interestingly, blocking NGF signaling can reduce sprouting in this same model and has been proposed as an alternative approach to pain management for osteosarcoma-induced pain." (PMID 41228327, 2025). "This insight means that NGF could potentially be a therapeutic target in clinical research on osteosarcoma." (PMID 38816365, 2024).
osteosarcoma (continued). "However, in wound healing, transwell migration, and invasion assays, the migration ability of 143B/NGF cells was significantly higher than that of 143B cells, thereby demonstrating that endogenous NGF can control the motility of osteosarcoma cells." (PMID 38816365, 2024). "This study found that NGF induces metastasis in osteosarcoma." (PMID 38816365, 2024). "We also examined the impact of NGF on the expression of four MMPs in osteosarcoma cells." (PMID 38816365, 2024). "In an in vivo xenograft model involving the subcutaneous injection of osteosarcoma cells into the right flank of mice, it was found that the resulting tumor volume and weight of the overexpressing NGF cell line (143B/NGF) were markedly greater than those of the 143B cell line." (PMID 39247831, 2024). "Incubating osteosarcoma cells with NGF was shown to augment FAK and c-Src phosphorylation." (PMID 39247831, 2024). "Experiments in the current study confirmed that the oral administration of the TrK inhibitor larotrectinib significantly inhibited the effects of NGF on M2 macrophage levels and osteosarcoma progression; however, it is important to consider the complexity of the in vivo tumor microenvironment." (PMID 39247831, 2024). "It is also a novel candidate for targeting the NGF-mediated progression of osteosarcoma." (PMID 39247831, 2024). "The current study was based on the hypothesis that MMP-2 is an important factor in the NGF-induced migration of osteosarcoma." (PMID 38816365, 2024). "Moreover, the inhibition of FAK and c-Src countered the decrease in miR-513c-5p synthesis induced by NGF, which suggests that NGF modulates VCAM-1-dependent monocyte adhesion to osteosarcoma cells by inhibiting miR-513c-5p levels via the FAK and c-Src pathways." (PMID 39247831, 2024). "Therapeutic interventions targeting NGF/BDNF–Trk and neural co−regulatory pathways in osteosarcoma immunity: targets, mechanistic rationale, pharmacodynamic biomarkers, and combination strategies." (PMID 41383615, 2025). "Taken together, NGF-TrkA, BDNF-TrkB and GDNF–RET circuits endow osteosarcoma cells with proliferative, anti-apoptotic and pro-metastatic properties." (PMID 41142827, 2025). "This mini review synthesizes current knowledge on NGF/TrkA and BDNF/TrkB axes in osteosarcoma with emphasis on neurotrophin-driven remodeling of antitumor immunity." (PMID 41567220, 2025). "The purpose of this review is to synthesize current evidence and propose a translational roadmap for targeting NGF/TrkA and BDNF/TrkB to remodel antitumor immunity in osteosarcoma." (PMID 41567220, 2025). "NGF/TrkA and BDNF/TrkB constitute actionable determinants of osteosarcoma progression and antitumor immunity." (PMID 41567220, 2025). "In osteosarcoma cells, inhibition of MEK or ERK, via small molecule inhibitors or siRNA, reversed NGF-mediated downregulation of miR-92a-1-5p." (PMID 41163091, 2025). "Core features of NGF/TrkA and BDNF/TrkB signaling relevant to osteosarcoma biology and antitumor immunity." (PMID 41567220, 2025). "NGF–TrkA shows highest expression; BDNF–TrkB and GDNF–GFRα/RET are variable, whereas NT−3/TrkC is low in osteosarcoma but prominent in other bone sarcomas, hence our emphasis." (PMID 41142827, 2025). "In our study, larotrectinib significantly inhibited NGF-induced PDGF-C expression and angiogenesis in MG63 osteosarcoma cells." (PMID 39860039, 2025). "The collective evidence positions NGF/TrkA and BDNF/TrkB as context-dependent organizers of osteosarcoma biology and its immune microenvironment." (PMID 41567220, 2025). "This research also provided evidence that NGF significantly downregulates the expression of miR-92a-1-5p, thereby promoting MMP-2 expression and osteosarcoma metastasis." (PMID 38816365, 2024). "In the current study, we determined that NGF facilitates VCAM-1-dependent monocyte adhesion and M2 polarization in the osteosarcoma microenvironment." (PMID 39247831, 2024).